CCL4 (C-C motif chemokine ligand 4)
Diseases named in the same sentence as CCL4 in open-access papers (continued):
Sharing a sentence is not in itself a finding about the gene and the disease.
tumor (continued). "Basophils not only enhance humoral immune function but also liberate intracellular agents causing anti-tumor immunity, including the chemokines CCL3 and CCL4, which expedite CD8+ T-cell infiltration, and the chemokines TNF-α and IL-6, which enhance inflammatory anti-tumor responses." (PMID 39816393, 2024). "TAM-produced CCL4, along with CCL5, may also facilitate the recruitment of bone marrow-derived monocytes to the tumor site." (PMID 39068459, 2024). "Furthermore, upon treating various types of tumour cell lines with FOXO1 inhibitors, we observed not only the upregulation of VEGFC, PD‐L1 and CCL4 but also varying degrees of increase in MOMP‐related molecules (such as BAX, BAK1, CASP3, STING, IRF3 and RELB)." (PMID 38899748, 2024). "In conclusion, the study suggested that CCL4/CCL5 may interact with their receptors, CCR1/CCR5, facilitating the recruitment of γδ T cells to tumor regions." (PMID 38338658, 2024). "Similarly, immunofluorescence staining in tumoural liver 2 weeks after intraportal injection of KPC cells in wild-type mice indicated that CCL3, CCL4 and CCL5, and IL-12, IL-15 and IL-18 are most prominently produced by KCs present at the tumour margin." (PMID 38326607, 2024). "Furthermore, ectopic expression of ID3 in hiPSC-Macs also increased their production of the chemokines CCL3, CCL4 and CCL5, and the cytokines IL-12, IL-15 and IL-18 in response to tumour cells in vitro." (PMID 38326607, 2024). "Immunofluorescence staining confirmed that the expression of chemokines CCL3, CCL4 and CCL5 and the cytokines IL-12, IL-15 and IL-18 by KCs in the liver of Clec4fcreId3f/f mice was reduced or abolished at the tumour margin and in the tumour in comparison to in the littermate controls." (PMID 38326607, 2024). "In conclusion, they proposed that the interaction between CCL4/CCL5 and their receptors may facilitate the recruitment of γδ T cells to tumor regions." (PMID 38338658, 2024). "Chemokines, such as CCL4, CCL5, and XCL1, released from a wide range of cell sources, are key chemoattractants for cDC1s to infiltrate from periphery lymphoid compartments into neoplasms." (PMID 39107856, 2024). "HLA-DRA also showed a surprising positive correlation with CCL4, CCL5, CXCL9, and CXCL10, indicating its beneficial role in the human immune response through inducing immune cell infiltration and improving tumor clearance in the body." (PMID 38931345, 2024). "These three signatures consist of myeloid-focused cytokines (TNFa, GM-CSF, and IL-1b), chemokines (CCL3, CCL4, CCL5, CXCL9, and CXCL10), and an effector T-cell-derived cytokine (IFNg) and represent important aspects of a macrophage-based anti-tumor immune response." (PMID 39199551, 2024). "Furthermore, proinflammatory cytokines including CXCL9, TNF-α, CCL4, and CCL3 were also upregulated in the tumor following the combined therapy, further demonstrating the change in the immune environment." (PMID 38705987, 2024). "The expression of CCL3, CCL4, and CCL5 chemokines, also higher, may be major determinants of tumor infiltration by DCs and NKs." (PMID 37675835, 2023). "The CCL4 level did not change in the serum or tumor samples, and the IL-10 level did not change in the samples from the serum." (PMID 37112810, 2023). "Additionally, CDKN2A experienced different forms of genetic alteration under tumor conditions, a characteristic that influenced the infiltration and the status of CD8, the chemokine CCL4, and the chemokine receptor CCR6." (PMID 37626750, 2023). "Inflammatory responses occur at the early stage after LITs, increasing the permeability of tumor vessels and promoting the injured tumor cells to produce chemokines (e.g., CCL2, CCL3, CCL4, CCL8, etc.)and proinflammatory cytokines (e.g., TNF-α, IL-1, IL-6, IL-17, etc.)." (PMID 36831664, 2023).
tumor (continued). "When administered to mice, the complex inhibited tumor growth, reduced signs of general toxicity, neurotoxicity and cardiotoxicity, increased the immune response (serum levels of IFN-γ, TNF-α and chemokines CCL4 and CCL17) and prolonged animal survival." (PMID 36672622, 2023). "By modulating the expression or activity of CCL4 and CCL5, it may be possible to modulate the immune cell composition and activity within the TME, thereby impacting the tumor immune response." (PMID 38067251, 2023). "MDSCs are generated in the bone marrow and their recruitment to the tumor site is dependent on diverse set of chemokines, such as CCL2, CCL3 and CCL4, for the recruitment of M-MDSCs via the C-C chemokine receptor 2 (CCR2) and the ligands of the CXC-chemokine receptor 2 (CXCR2) for PMN-MDSC." (PMID 37370739, 2023). "Indeed, CCL2 will recruit macrophages to the tumor, and induce their production of VEGF as will CCL4." (PMID 35626056, 2022). "Ultimately, further investigation into both CCL4 and CCL3L1’s roles in mediating tumor immune infiltration following NACT exposure is warranted, as it could potentially lead to original approaches to combat the immunosuppressive ovarian TIME." (PMID 36131935, 2022). "By migrating to the tumor, MDSC elevates Arg1 and iNOS, downregulating ROS production, upregulating PD-L1 on MDSC surface, and producing CCL4 and CCL5 chemokines to attract T-regs, strongly suppressing the activity of CTLs and NK cells in the tumor microenvironment." (PMID 35214123, 2022). "In summary, our data support a model by which cancer-driven protumoral myelopoiesis is regulated by a circuit in which tumor derived factors induce the production of CCL3 and CCL4 and other CCR1 and CCR5 ligands that, by engaging CCR1 and CCR5, autocrinally promote their differentiation into MDSCs." (PMID 35064009, 2022). "Therefore, we proposed that malignant TCyEM cells appeared to produce high levels of CCL5 and CCL4 to recruit and polarize CD163-expressing M2 TAMs, forming a tumor-supporting environment in TCyEM cases." (PMID 35241665, 2022). "Tumor-infiltrating MDSCs could also recruit CCR5+ Tregs to the tumor site through releasing CCR5 ligands CCL3, CCL4, and CCL5 to promote tumor growth in a B16 melanoma model." (PMID 35267547, 2022). "Second, analyses performed on tumor lysates revealed that chemokines involved in myeloid cell migration (CCL5, CCL2, CCL4), together with inflammatory (IL-1β and TNFα) and pro-angiogenic factors (VEGF-A, VEGFR2, PDGF, Endoglin) were increased in tumors of mice fed a HFHCD." (PMID 36104342, 2022). "Interestingly, some reports have proven that patrolling monocytes can recruit large numbers of NK cells to tumor sites, especially metastatic tumor lesions, through the release of cytokines, such as CCL3, CCL4, and CCL5 47-49." (PMID 36438484, 2022). "Comparing immune cells and immune-related gene expression across different FAT statuses, we found that in FAT mutant STAD, chemokines, such as CCL3, CCL4, CXCL1, CXCL3, CXCL9, and CXCL10, recruited and activated cytotoxic T lymphocytes in the tumor tissue to perform an antitumor effect." (PMID 35836939, 2022). "However, Mono-FCGR3A in high tumor infiltration group expressed lower levels of MHC molecules, inflammatory cytokines and chemokines (HLA-DRB1/HLA-DPB1, TNF, IL1B, CCL3 and CCL4), which meant the sub-cluster was less involved in immune responses." (PMID 36532059, 2022). "Interestingly, CCR5 ligands: CCL3, CCL4 and CCL5 were detected in the majority of supernatants harvested from dissociated tumour biopsy and CUSA, but little was detected in GNS cell supernatants." (PMID 35464424, 2022). "Considering that CCL4 acts as a chemokine, we hypothesized that SLC7A1 is involved in regulating tumor-infiltrating immune cells (TICs)." (PMID 36131790, 2022).
tumor (continued). "Besides, MDSCs can produce high levels of some chemokines, such as CCL3, CCL4, and CCL5, which drive CCR5-expressing Treg cells through the tumor microenvironment, supporting the tumor growth." (PMID 35757002, 2022). "Moreover, the data showed a correlation between CCL4 levels and number of PMN-MDSCs in circulation (R2 = 0.5106) as well as tumor weight (R2 = 0.3670)." (PMID 36970050, 2022). "(ii) Antitumor immune-related molecules including CXCL10, CXCL9, CXCR3, CCL5, and CCL4 belong to the chemokine family and have been reported in several studies to recruit immune cells such as cytotoxic T lymphocytes (CTL) and NK cells to kill tumor cells." (PMID 35479936, 2022). "The qPCR results confirmed the upregulation of Coro7 (p = 0.04), Ccl4 (non-significant) and Gcnt2 (p = 0.011) in the caerin treated tumour bearing mice when compared to untreated mice." (PMID 36497272, 2022). "Not coincidentally, the combination of CCL19/21 with CCL4 can also be used as an adjuvant for DNA vaccination in Her2/neu mouse tumor models." (PMID 35770088, 2022). "Tumor CCL2 and CCL7 increased along with advancing T and CCL3, and CCL4 along with the N stage." (PMID 34885960, 2021). "Meanwhile, EE-induced a higher NE level in the bone marrow and a higher EPI level in the spleen in DEN + CCL4-induced tumor-bearing mice, where EE did not affect EPI or NE in the bone marrow and spleen of normal mice." (PMID 34593796, 2021). "Examples include RIVAL 01/TBio-6517, a Vaccinia virus for tumor-directed expression of FLT3L, anti-CTLA-4, and IL-12 (NCT04301011), and ONCR-177 (NCT04348916), an HSV-1 mediating expression of IL-12, FLT3LG, CCL4, anti-PD-1, and anti-CTLA-4 to enhance induction of tumor-specific adaptive immunity." (PMID 33863363, 2021). "The results indicated that high CCL4 expression might give rise to high immune infiltration levels and be positively correlated with TME characteristics, excluding tumor purity." (PMID 34900664, 2021). "Moreover, pro-inflammatory cytokines (IFN-γ, TNF-α) and chemokines (CCL3, CCL4, and CCL5) secreted by NK cells stimulate other lymphocyte populations in the tumor microenvironment or exert a direct anti-tumor effect." (PMID 34203935, 2021). "Interestingly, while the upregulation in tumors is markedly higher for CCL4 and CXCL2, the CCL2, CCL8 and CCL19 transcripts are relatively downregulated in tumors compared to tumor-adjacent tissue." (PMID 34885960, 2021). "Differential expression analysis of pre- and post-treatment tumor-infiltrating MAIT cells revealed upregulation of the activation marker HLA-DRB1, the cytotoxic effector GZMH, and the chemokines CCL4 and CCL5 following anti-PD-1 therapy in both types of cancer." (PMID 32849590, 2020). "It remains to be explored whether adoptive transfers using lower CTL numbers or earlier following tumour engraftment would result in a more dominant role for CCL3 and CCL4-mediated homotypic signalling in recruitment into solid tumours." (PMID 33046212, 2020). "(D) Average speed (Left) and FMI (Right) of CTLs adjacent to tumouroids containing control or CCL3/CCL4-secreting EL4 tumour cells compared with non-cognate and SIINFEKL-pulsed cognate tumouroids pre-embedded with tumour-reactive CTLs." (PMID 33046212, 2020). "In the current study, we explored the potential mechanism of Porf-2 in tumor cell migration by screening several key proteins, such as adhesion molecules (ICAM1, VCAM1, E-cadherin), chemokines (CCL4, CXCL4) and their receptors (CXCR4/6/7), integrins (integrin α1/β1/β3), and MMPs (MMP-2/3/7/9)." (PMID 32676454, 2020). "Moreover, blocking CCL4 inhibited the increase of memory CD8+ T cells and tumor-specific CD8+ T cells mediated by the combination of CBDCA and anti-PD-1 antibodies in the 4T1 tumors, as well as other two models." (PMID 32194569, 2020). "MIF-induced CCL4 and MMP9 production in TANs may have tumor autonomous effects by promoting lymphangiogenesis as well as tumor-stromal remodeling." (PMID 33324425, 2020).
tumor (continued). "Besides M‐CSF, the CC chemokines CCL2, CCL3, CCL4 and CCL5 are well‐recognized chemotactic factors for macrophage populations in the tumour." (PMID 33025708, 2020). "It is possible that CCL4-producing CD45+ leukocytes also play a role in CD103+ DC recruitment into the tumor in this context, although leukocytes are not a majority of the cellular source of CCL4." (PMID 32194569, 2020). "Cytokines released from tumor-residing cells including tumor cell–derived IL-4, IL-10, CCL2, CCL3, CCL4, and CSF1; Treg-derived IL-10; B cell–produced immunoglobulins; Th2-derived IL-4 and IL-13; and MSC-derived MFG-E8 promote the polarization into a protumor phenotype." (PMID 31256327, 2020). "CCL3, CCL4, IL-1α and IL-12/IL23p40 were highest in individuals with no adverse features of tumor biology, whereas levels of Tie2 and VEGF were lowest in this cohort." (PMID 33202734, 2020). "Moreover, examination of cytokine/chemokine production in the tumor microenvironment revealed an increase in the levels of chemoattractive cytokines such as CCL3, CCL4, CCL5, CXCL9, CXCL10 and CXCL11." (PMID 32033490, 2020). "The number of macrophages and levels of IFNγ and macrophage inflammatory protein-1β (CCL4) mRNA, were markedly reduced in tumors from CHOP KO mice as compared to wild-type mice, suggesting a role for CHOP in modulating the tumor microenvironment and macrophage recruitment to the tumor." (PMID 32560326, 2020). "NK cells play a critical role in anti-tumor immunity and they could respond to several chemokine signals, including CCL3/CCL4/CCL5 via CCR5 and CXCL9/CXCL10 via CXCR340–42." (PMID 30718511, 2019). "And CCL4/MIP-1β, which is produced by immature myeloid cells, could recruit Th17 cells to tumor sites." (PMID 30800130, 2019). "There are no previous data on CCL2, CCL3 or CCL4 in PitNETs, but these chemokines are involved in tumour growth and invasion in other tumours, as well as in immune cell chemotaxis in cancer." (PMID 31703742, 2019). "In addition, we observed a significant correlation between CCL4 and VEGF-C levels in serum samples as well as a significant correlation between VEGF-C mRNA expression and circulating VEGF-C in tumor specimens." (PMID 29599774, 2018). "Multiple Th1 cytokines and downstream targets were overexpressed in hot tumours (IFNG, CCL4, CCL5, CXCL9, CXCL10), along with costimulatory and coinhibitory receptors, suggesting these tumours were marked by a state of lymphocyte activation and counter-responses thereto." (PMID 30104673, 2018). "Here, most HPV-positive tumors separated into clusters, mainly due to differences in the expression of immune related proteins on the cell surface of tumor infiltrating immune cells, e.g., PD-1, FasL, NCR1, and KLRD1 or soluble cytokines/chemokines e.g., IL12 and CCL4." (PMID 29587383, 2018). "In summary, suppression of GBM tumor growth correlated with reduction of immune suppressive cells (Treg and MDSC), an increase of tumor killing macrophages (M1), and reduction of markers of chronic inflammation (CCL4 and IFNγ) in the tumor microenvironment." (PMID 28512255, 2017). "Exosomes derived from heat-stressed tumor cells (HS-TEX) which contain chemokines, such as CCL2, CCL3, CCL4, CCL5, and CCL20, could chemoattract and activate dendritic cells (DC) and T cells more potently." (PMID 29164149, 2017). "The increased macrophage recruitment may be a response to the increased chemokine release by tumor cells such as CXCL-10, CCL-2, CCL3, CCL4, and CCL5." (PMID 28670313, 2017). "Indeed, chemokines such as CCL3, CCL4, CCL5 and CXCL10 were significantly increased in tumours injected with MV-Edm." (PMID 28701757, 2017). "In addition, it is well known that CCL3, CCL4 and CCL20 are able to recruit T cells containing CTLs to the tumor site." (PMID 29079795, 2017).
tumor (continued). "Orally fed iron saturated bLf-Dox inhibited tumour development, prolonged survival, reduced Dox induced general toxicity, cardiotoxicity, neurotoxicity in TRAMP mice and upregulated serum levels of anti-cancer molecules TNF-α, IFN-γ, CCL4 and CCL17." (PMID 27576789, 2016). "Upon tumour antigen pulsing, high levels of chemokines that sustain the recruitment of circulating DCs to inflamed tissues, such as CCL3, CCL4, were expressed, whereas at late time-points constitutive lymphoid chemokine such as CCL2, CCL8, CXCL10, CXCL12 and RANTES were selectively up-regulated." (PMID 26795765, 2016). "More importantly, Fe-bLf Dox was capable of inducing greater expression of anti-tumour and macrophage homing chemokines such as GM-CSF (1.7 fold), CCL11 (1.8 fold), IL-1ra (1.3 fold), IL-23 (1.5 fold), CCL12 (1.8 fold), CCL4 (1.5 fold) and CCL17 (1.7 fold), than Dox injections." (PMID 27576789, 2016). "The expression of Ccr5 and its ligands, Ccl3 and Ccl4, but not Ccl5, were markedly increased in tumor sites 7 days after the injection." (PMID 27340784, 2016). "Likewise, in an experimental melanoma model, tumor-infiltrating Tregs expressed CCR5 and preferentially migrated toward its ligands CCL3, CCL4, and CCL5, which were elaborated by tumor-infiltrating myeloid-derived suppressor cells (MDSCs)." (PMID 26217588, 2015). "EpCAM (p = 0.0001), IL8 (p = 0.0003), CCL4/MIP-1β (p = 0.0026), CCL20/MIP-3α (p = 0.039) and TIMP1 (p = 0.0017) tissue protein levels were significantly different (Mann Whitney U test) between tumours versus AN & PN." (PMID 21092330, 2010). "In addition, they also indirectly shift the balance between tumor reactivity and tumor tolerance by recruiting through e.g. CCL3, CCL4, and CCL5 as well as be promoting the induction of T cell-suppressive Tregs through the release of IL-10 or TGF-β, among others." (PMID 40050933, 2025). "Moreover, the expression of chemokines such as CCL3,CCL4, and CCL5 may influence T cell recruitment and localization, further exacerbating the immunosuppressive state in the tumor microenvironment." (PMID 41394809, 2025). "Furthermore, a recent investigation on CRC has revealed that the TIME specifically endowed TAMs with elevated inhibitor of differentiation 1 expression, which interacted with STAT1 to suppress the chemoattractant CCL4, thereby excluding CD8+ T cells from tumor parenchyma." (PMID 39107856, 2024). "Furthermore, the Mast-CCL2 subgroup may activate the NF-κB signaling pathway through TNF-α, potentially playing a role in the recruitment of peripheral blood monocytes to the tumor by expressing CCL2 and CCL4 genes, thereby exerting effects in BCa." (PMID 39308672, 2024). "Next, we asked if CDKN2A alteration could affect other immune components; therefore, we checked the correlation of CDKN2A alteration with the chemokine CCL4 and the chemokine receptor CCR6, which are known for their immunosuppressive roles against tumor development." (PMID 37626750, 2023). "In contrast, Th1‐like CD4+ T cells, characterized by the expression of CCL4, GZMA and GZMB were found to be involved in viral protein interactions, natural killer cell‐mediated cytotoxicity and the T cell receptor signaling pathway, revealing their positive roles in tumor immune defense." (PMID 36725337, 2023). "Interestingly, OVs induce a strong antiviral tumor immune response through the production of cytokines like type-1 interferon that in turn promotes PD-L1 expression on tumor cells and also cytokines, such as CCL3 and CCL4, attracting PD-1+ or CTLA-4+ immune cells within TME." (PMID 35392236, 2022). "We demonstrate that CCL4 promotes Angpt2 expression in OSCC by activating signal transducer and activator of transcription 3 (STAT3) and mitogen-activated protein kinase kinase (MEK), signal-regulated kinase 1/2 (ERK) signaling, which subsequently enhances Angpt2-induced tumor angiogenesis." (PMID 35884919, 2022).